TIMP1 (TIMP metallopeptidase inhibitor 1)
Diseases named in the same sentence as TIMP1 in open-access papers (continued):
Sharing a sentence is not in itself a finding about the gene and the disease.
muscular dystrophy (2 papers, 2007 to 2021). Muscular dystrophy (MD) refers to a group of more than 30 genetic diseases characterized by progressive weakness and degeneration of the skeletal muscles that control movement. "TIMP1/2, natural inhibitors of matrix metalloproteinases (MMPs), are good candidates because upregulation of MMP9 is reported to promote fibrosis in muscular dystrophy." (PMID 34627382, 2021). "One report mentioned that expression of TIMP-1 and TIMP-2 mRNA levels were not different between inflammatory myopathies/inclusion body myositis and muscular dystrophy." (PMID 17598883, 2007).
Neonatal sepsis (2 papers, 2017 to 2024). Systemic inflammatory response to infection in newborn babies. "AF-MMP-9 (p = 0.006), MPO (p = 0.011), HNE (p = 0.034), and MMP-8/TIMP-1 molar ratio (p = 0.034) were associated with blood culture positive neonatal sepsis when the data were adjusted by gestational age at delivery (data not shown)." (PMID 28167848, 2017).
neuroblastoma (2 papers, 2017 to 2023). Neuroblastoma (NB) is the most common solid, extracranial childhood tumor. "Utilizing publically-available datasets, we have demonstrated that high TIMP-1 gene expression is significantly associated with disease relapse and mortality in patients with neuroblastoma." (PMID 29137288, 2017). "Together, these findings demonstrate that increased levels of TIMP-1 are associated with disease relapse and mortality in patients with neuroblastoma." (PMID 29137288, 2017). "Taken together, our study identifies TIMP-1 as a novel soluble factor that is associated with a prometastatic phenotype in our in vivo model and adverse outcomes in patients with neuroblastoma." (PMID 29137288, 2017). "Taken together, this study demonstrated that TIMP-1 is capable of modulating neuroblastoma growth in vitro, and elevated expression is associated with a prometastatic phenotype in our liver metastasis model and adverse patient outcomes and mortality." (PMID 29137288, 2017). "Similar to reports in adult cancer, high TIMP-1-expressing tumors in our small, advanced stage neuroblastoma tissue microarray (N= 20 tumors) was associated with increased adverse events and mortality." (PMID 29137288, 2017). "We broadened these observations to two larger, established neuroblastoma databases within the R2 platform and have identified elevated TIMP-1 expression to be associated with disease relapse and poor patient survival." (PMID 29137288, 2017). "We chose to characterize the effects of modulating endogenous TIMP-1 expression in neuroblastoma cells utilizing RNA interference." (PMID 29137288, 2017). "Specifically, we utilized the neuroblastoma databases of Versteeg and Kocak to generate a Kaplan-Meier Curve based upon TIMP-1 gene expression utilizing the R2: microarray analysis and visualization platform." (PMID 29137288, 2017). "Immunoblotting and ELISA demonstrated enhanced endogenous TIMP-1 expression in our isolated neuroblastoma subclone." (PMID 29137288, 2017). "We utilized publically accessible clinical databases to further evaluate the relationship between TIMP-1 expression and patient prognoses in larger, independent cohorts featuring all stages of neuroblastoma." (PMID 29137288, 2017). "To ascertain the clinical relevance of high TIMP-1 expression in neuroblastoma, we correlated TIMP-1 expression by immunohistochemistry in our tissue microarray for advanced stage human neuroblastomas to patient outcomes." (PMID 29137288, 2017). "Taken together, these findings suggest that TIMP-1 may play a role in advanced stage neuroblastoma progression." (PMID 29137288, 2017). "Notably, tissue microarray analysis and Kaplan-Meier by gene expression demonstrates that elevated TIMP-1 expression is correlated with increased disease relapse and mortality in patients with neuroblastoma." (PMID 29137288, 2017). "Interestingly, targeted down-regulation of TIMP-1 (siTIMP-1 or shTIMP-1) using interfering RNA in neuroblastoma decreased in vitro proliferation in adherent, soft agar, and neurosphere conditions, but failed to impede the prometastatic LM2 phenotype in our liver metastasis model." (PMID 29137288, 2017). "As such, we hypothesized that TIMP-1 may be a critical regulator of metastasis in neuroblastomas." (PMID 29137288, 2017). "As such, we concluded that suppression of endogenous TIMP-1 in our aggressive neuroblastoma subclone was not sufficient to rescue its prometastatic properties within our metastasis model." (PMID 29137288, 2017).
neuroendocrine tumors (2 papers, 1996 to 2024). "Previous analysis of TIMP1 expression levels using immunohistochemistry has shown significantly elevated levels in gastroenteropancreatic, bronchopulmonary, and primary skin neuroendocrine tumors as well as the glandular epithelium of IBD." (PMID 39233736, 2024).
non-Hodgkin lymphoma (2 papers, 2010 to 2017). Distinct from Hodgkin lymphoma both morphologically and biologically, non-Hodgkin lymphoma (NHL) is characterized by the absence of Reed-Sternberg cells, can occur at any age, and usually presents as a localized or generalized lymphadenopathy associated with fever and weight loss. "Leukemic blasts have been shown to have higher levels of TIMP-1 transcripts and increased TIMP-1 expression was also observed in Non-Hodgkin lymphomas and Burkitt B-cell lymphoma cell lines." (PMID 27903985, 2017).
oropharyngeal cancer (2 papers, 2019 to 2025). Carcinoma, predominantly squamous cell, arising from the epithelial cells of the oropharynx. "In the available literature concerning oropharyngeal cancers, an increase in TIMP-1 progression was observed in tumors with a higher degree of organ and regional staging." (PMID 31223594, 2019).
osteonecrosis (2 papers, 2023 to 2024). A none disease characterized by death of bone tissue due to a lack of blood supply. "Matrix metalloproteinase-9 (MMP-9) and tissue inhibitor of metalloproteinases-1 (TIMP-1) are involved in the pathological mechanism of osteonecrosis of the femoral head (ONFH)." (PMID 36991363, 2023). "Last, high levels of MMP-9 along with an imbalance in the MMP-9/TIMP-1 ratio have been found in patients with idiopathic, alcohol- and steroid-induced nontraumatic osteonecrosis of the femoral head and correlated with the development and severity of osteonecrosis." (PMID 39590837, 2024).
pancreatic disease (2 papers, 2017 to 2022). "We evaluated TIMP-1 and CD82 expression by immunohistochemistry in 32 cases of histological or cytological confirmed pancreatic diseases." (PMID 28030805, 2017).
peripheral nerve injury (2 papers, 2018 to 2019). Injury to a peripheral nerve. "Because TIMP-1 and MMPs can be up-regulated simultaneously during tissue damage and repair, such as in peripheral nerve injury, disentangling how TIMP-1 regulates tissue remodeling/repair from the induction of pain, per se, is challenging." (PMID 31616247, 2019). "Peripheral nerve injury has been shown to induce TIMP-1 expression in the DRG." (PMID 29945607, 2018).
Peritoneal Fibrosis (2 papers, 2014 to 2023). Disorder characterized by a wide range of structural changes in PERITONEUM, resulting from fibrogenic or inflammatory processes. "When standardized against TIMP-1 levels, this reflected a significant decrease in the MMP-3/TIMP-1 ratio, which would predict increased matrix deposition and peritoneal fibrosis." (PMID 24412616, 2014).
peritonitis (2 papers, 2013 to 2019). Inflammation of the peritoneum (tissue that lines the abdominal wall and covers most of the organs in the abdomen). "MMP-2 was associated with chemical peritoneal injury and showed increased levels in PD effluent in patients with peritoneal injury, while PD effluent levels of MMP-9 and TIMP-1 were higher in the onset of peritonitis." (PMID 31815017, 2019).
pneumothorax (2 papers, 2012 to 2020). Abnormal presence of air in the pleural cavity. "In summary, the expression of MMP-9 and TIMP-1 in COPD patients with spontaneous pneumothorax was higher than that in normal controls, but the expression was not correlated with arterial blood gas parameters." (PMID 32063958, 2020). "The serum expressions of TIMP-1 and MMP-9 in 80 COPD patients complicated with spontaneous pneumothorax (COPD group) and 52 healthy volunteers (control group) were detected by ELISA." (PMID 32063958, 2020).
prostate adenocarcinoma (2 papers, 2014 to 2025). "TIMP-1: Biochemical analysis, in situ hybridization and immunohistochemistry studies have clearly shown that TIMP-1 expression is lost in the tumor tissue of prostate adenocarcinoma cells and many other solid tumors." (PMID 24978435, 2014). "Analysis of prostate adenocarcinoma samples from the GEPIA and UALCAN databases revealed significantly lower TIMP1 mRNA expression in tumor tissues compared with adjacent normal tissues (p < 0.001)." (PMID 40185230, 2025).
rectal adenocarcinoma (2 papers, 2025). "The signature comprises three macrophage-related genes—TIMP1, MAOB, and PYGM—that robustly stratify rectal adenocarcinoma (READ) patients by prognosis." (PMID 40873584, 2025).
rectal tumors (2 papers, 2006 to 2014). "In both colon and rectal tumors, MMP-2, MMP-9 and TIMP-1 protein levels were higher than in corresponding paired normal mucosa, while TIMP-2 level in tumors was significantly lower than in normal mucosa." (PMID 16916471, 2006).
relapsing-remitting MS (2 papers, 2009 to 2018). "High serum MMP9 and low TIMP1 levels were associated with brain lesion formation in relapsing-remitting MS, and a decrease in the ratio was associated with interferon treatment." (PMID 28361271, 2018). "MMP-9/TIMP-1 ratio may be viewed as a reliable marker and may be predictive of MRI activity in relapsing-remitting MS." (PMID 19490629, 2009).
renal dysfunction (2 papers, 2015 to 2021). "Multiple regression analysis showed an association for TIMP-1 (p = 0.004) with impaired neurophysiological examinations and renal dysfunction along with NGAL (p = 0.016 and p = 0.015 respectively)." (PMID 33775157, 2021).
retinal detachment (2 papers, 2020 to 2024). An eye emergency condition which may lead to blindness if left untreated. "In terms of RD-free survival, the Kaplan–Meier curve demonstrated a significant correlation between the initial aqueous humor TIMP-1 levels and the risk of retinal detachment (RD) (P = 0.035)." (PMID 39723192, 2024).
retinitis pigmentosa (2 papers, 2018 to 2024). Retinitis pigmentosa (RP) is an inherited retinal dystrophy leading to progressive loss of the photoreceptors and retinal pigment epithelium and resulting in blindness usually after several decades. "The exogenous application of TIMP-1 has been reported to significantly modulate the mosaics and restore their homogeneity in the retina of the rat model of retinitis pigmentosa and may be a potential therapeutic agent." (PMID 39723192, 2024).
sarcoma (2 papers, 2013 to 2019). A usually aggressive malignant neoplasm of the soft tissue or bone. "Whereas the TIMP1 and TIMP3 co-expressed gene profiles from cancers of various origins were more interspersed with less apparent grouping of any specific cancer type (carcinoma, sarcoma, hematologic)." (PMID 31882975, 2019). "Other authors reported that no or minimal expression of TIMP-1 was detected in musculoskeletal sarcomas, and that there was a significant decrease of serum the TIMP-1 levels in sarcoma patients compared to healthy controls." (PMID 23799912, 2013).
serous adenocarcinoma (2 papers, 2009 to 2020). An adenocarcinoma that is characterized by the presence of papillary patterns and cellular budding. "For that, TIMP1 gene expression was knocked-down in SKOV3 cell line, since this cell line represents serous carcinomas and expresses high levels of the marker." (PMID 32423054, 2020).
serous ovarian cancer (2 papers, 2020 to 2021). "In addition, increased expression levels of MMPs, including MMP-2, MMP-7, and MMP-9, as well as TIMPs, including TIMP-1 and TIMP-2, were observed in mucinous ovarian cancer compared with those in serous ovarian cancer." (PMID 32197606, 2020). "Even though the TCGA datasets from three studies on 1680 serous ovarian carcinomas suggests a prognostic utility (OS and PFS) of MMP-14 based on its altered and unaltered genetic expression in serous ovarian cancer patients, no such links could be made with TIMP-1, -3 or MMP-2, -9, and -11." (PMID 35047406, 2021).
Subarachnoid Haemorrhage (2 papers, 2020 to 2025). "Previous studies have shown that high expression of TIMP1 can inhibit inflammatory response, alleviate BBB injury, and repress EBI induced in subarachnoid hemorrhage model." (PMID 40604895, 2025).
thyroid nodule (2 papers, 2015 to 2024). A small circumscribed mass in the THYROID GLAND that can be of neoplastic growth or non-neoplastic abnormality. "In TC, TIMP1 expression was reported to be higher in malignant thyroid nodules than in normal thyroid tissues and benign thyroid nodules." (PMID 38770133, 2024).
thyrotoxicosis (2 papers, 2012 to 2013). A hypermetabolic syndrome caused by the elevation of thyroid hormone levels in the serum. "Radioiodine therapy of thyrotoxicosis does not alter serum MMP-2, MMP-9 or TIMP-1 concentrations either acutely or after about three months of observation." (PMID 23107223, 2012). "In summary, our study demonstrates that radioiodine treatment of thyrotoxicosis does not alter serum MMP-2, MMP-9 or TIMP-1 concentrations, either acutely or after about three months of observation." (PMID 23107223, 2012).
trachoma (2 papers, 2013 to 2014). "Scarring trachoma is also associated with differential expression of MMPs 7, 9, 10, and 12 and tissue inhibitor of MMP (TIMP)-1, and recurrence of trichiasis after surgery is associated with an altered MMP1/TIMP1 transcript ratio." (PMID 23457650, 2013).
transitional cell carcinoma of the bladder (2 papers, 2006 to 2021). "In a later study, this same author demonstrated similar behavior of tissue gene expression of MMP-9, TIMP-1, and RECK in patients with urothelial carcinoma of the bladder, with most patients overexpressing MMP-9 underexpressing TIMP -1 and RECK." (PMID 35097136, 2021).
tuberculous meningitis (2 papers, 2016 to 2022). "Similarly, elevated MMP-9 and the ratio of MMP-9 to tissue inhibitor of MMP-1 (TIMP-1) have been observed in the CSF of pediatric patients with bacterial meningitis, including tuberculous meningitis (TBM)." (PMID 35250814, 2022). "In this study, the levels of MMP-9 and its inhibitor, TIMP-1 (tissue inhibitor of metalloproteinases-1), were screened using zymography and reverse zymography in cerebrospinal fluid and serum of tuberculous meningitis patients at different stages of the disease." (PMID 27899068, 2016).
urinary tract infection (2 papers, 2020 to 2024). "Abedi and Mohammadjafari postulated that urinary MMP-9 and TIMP-1 may be markers of renal scarring in children with urinary tract infections." (PMID 32670438, 2020).
uveitis (2 papers, 2020 to 2024). An inflammatory process affecting a part of or the entire uvea. "Other genes were already implicated in other inflammatory disease models but not in uveitis, such as Lrg1, Ackr1 and Timp1." (PMID 32183784, 2020). "Our quantitative analysis, conducted on a large sample size of VZV-induced ARN patients, revealed significantly elevated levels of MMP-3 and TIMP-1 in the aqueous humor compared to virus-negative uveitis cases presenting with retinal inflammation." (PMID 39723192, 2024). "In this study, we aimed to quantitatively assess the levels of MMP-3 and TIMP-1 in the aqueous humor (AH) of ARN patients, using virus-negative uveitis (UV) patients as a control group." (PMID 39723192, 2024).
vesicoureteral reflux (2 papers, 2020 to 2024). Abnormal flow of urine from the urinary bladder back into the ureters. "Moreover, there are also studies that have demonstrated the clinical value of urinary MMP-9 and tissue inhibitor of metalloproteinase 1 (TIMP1) levels as novel biomarkers in identifying the risk of vesicoureteral reflux (VUR) and renal scar formation in children." (PMID 39766247, 2024). "Other authors suggested the usefulness of the measurement of urinary MMP-9 excretion and the urinary MMP-9/TIMP-1 ratio for the prediction of vesicoureteral reflux in neonates with antenatal HN." (PMID 32670438, 2020). "It was found that increased urinary excretion of TIMP-1 was observed particularly in patients with UPJO and vesicoureteral reflux." (PMID 32670438, 2020).
viral myocarditis (2 papers, 2013 to 2024). Myocarditis that is caused by an infection with a viral agent. "Consistent with the data obtained from viral myocarditis, we found that myocardial injury‐related genes including Timp1, AW112010, and Ctss were significantly increased by anti‐CTLA4 m2a antibody in the MZs of EAM mice." (PMID 38978328, 2024). "The same outcome was observed in vivo in a viral myocarditis model, and furthermore, Ad-IL-17AR:Fc intervention decreased MMP-2 significantly without significantly changing TIMP-1 expression." (PMID 23977238, 2013).
acute pancreatitis (1 paper, 2016). An acute inflammatory process that leads to necrosis of the pancreatic parenchyma. "We aimed to assess levels of MMP-7, -8, -9 and TIMP-1 in acute pancreatitis (AP) and explore their ability to detect disease severity." (PMID 27561093, 2016). "Levels of matrix metalloproteinase (MMP) -7,-8,-9 and tissue inhibitor of matrix metalloproteinase-1 (TIMP-1) in acute pancreatitis (AP) patients and controls." (PMID 27561093, 2016). "Statistical characteristics of MMP -8, -9 and TIMP-1 describing their ability to detect severe acute pancreatitis." (PMID 27561093, 2016). "We collected plasma samples for MMP-7, -8, -9 and TIMP-1 analyses from 176 patients presenting within 96 h from onset of acute pancreatitis (AP) symptoms." (PMID 27561093, 2016).
alcoholic cirrhosis (1 paper, 2022). "Notably, TIMP-1 is significantly reduced in viral and alcoholic hepatitis and alcoholic cirrhosis, possibly acting as a compensatory mechanism to facilitate ECM degradation." (PMID 36551935, 2022).
allergic conjunctivitis (1 paper, 2022). "On the contrary, MMP-9 was elevated, while the TIMP-1 levels were decreased in corneas with allergic conjunctivitis." (PMID 35692541, 2022).
ampullary cancers (1 paper, 1996). "The results implicate MMP2, MMP3 and TIMP1 in the invasive phenotype of pancreatic and ampullary cancer." (PMID 8611434, 1996).
anaplastic large cell lymphoma (1 paper, 2025). Anaplastic large cell lymphoma (ALCL) is a rare and aggressive peripheral T-cell non-Hodgkin lymphoma, belonging to the group of CD30-positive lymphoproliferative disorders, which affects lymph nodes and extranodal sites. "In anaplastic large cell lymphoma (ALCL) positive for anaplastic lymphoma kinase (ALK+), the aberrant overexpression of TIMP1 is directly associated with persistent STAT3 phosphorylation, thereby accelerating tumor progression." (PMID 41189944, 2025).
ankylosing spondylitis (1 paper, 2013). An autoimmune chronic inflammatory disorder characterized by inflammation in the vertebral joints of the spine and sacroiliac joints. "This study found higher levels of both MMP-3 and TIMP-1 in ankylosing spondylitis." (PMID 24078814, 2013).
Anxiety (1 paper, 2020). Intense feelings of nervousness, tension, or panic often arise in response to interpersonal stresses. "In particular, TIMP-1 was shown to impact memory and cognition in mice in an olfactory maze test and MMP-9 knockout mice exhibited lower anxiety in EPM and higher vertical activity in an open field test." (PMID 33384653, 2020).